CAV1 (caveolin 1)
Diseases named in the same sentence as CAV1 in open-access papers (continued):
Sharing a sentence is not in itself a finding about the gene and the disease.
cancer (continued). "To begin to understand the mechanism(s) underlying thelethality of a loss of Cav-1 in cancer-associated fibroblasts, we turned toCav-1 (-/-) deficient mice as a model system." (PMID 20442453, 2010). "Caveolin-1(-/-) null stromal cells are a novel genetic model for cancer-associatedfibroblasts and myofibroblasts." (PMID 20442453, 2010). "For this purpose, we isolated bone marrow derivedstromal cells from WT and Cav-1 (-/-) deficient mice, as cancer-associatedfibroblasts are thought to evolve from mesenchymal stem cells." (PMID 20442453, 2010). "Regarding its role in cancer, it has been established that PCa is associated with increased cav-1 expression." (PMID 19763272, 2009). "In patients, caveolin-1 presence is associated with angiogenesis, aggressive cancer recurrence, elevated metastasis of prostate tumours and poorer patient prognosis." (PMID 18400052, 2008). "Loss and overexpression of cav-1 has also been associated with the progression to a metastatic phenotype within different cancers." (PMID 15969750, 2005). "However, in advanced cancer stages, Cav1 transitions to an oncogenic role and is frequently associated with increased cancer cell survival, drug resistance, and metastatic potential." (PMID 40963741, 2025). "However, systemic application of aspirin or other drugs inducing enhanced expression of CAV1 can also cause overexpression of CAV1 in cancer cells, leading to a corresponding reduction in their radiosensitivity." (PMID 41516288, 2025). "Further research into the role of Cav1 in EV-mediated cancer progression could pave the way for improved diagnostic tools and novel therapeutic strategies in cancer treatment." (PMID 40963741, 2025). "In cancer, several studies have linked Cav-1 to metabolic reprogramming." (PMID 40243482, 2025). "Notably, aberrant Cav-1 phosphorylation has been implicated in pathological conditions, including cancer metastasis and cardiovascular disease, highlighting its potential as a therapeutic target." (PMID 40243482, 2025). "Indeed, under the oxidative stress attack induced by cancer cells, the reverse Warburg effect has been proposed to result from a loss of caveolin-1 in stromal fibroblasts, or to an OXPHOS downregulation in these cells with consequent glycolytic predominance." (PMID 40558563, 2025). "The molecular mechanism of IFITM 1 in cancer generally remains poorly examined, but may include, among others, regulation of matrix metalloproteinases, caveolin-1, and other proteins associated with cell migration and adhesion." (PMID 38653773, 2024). "We further examined whether the distribution of Ago2 between the fractions of plasma membranes, which are enriched with CAV1, and other membrane organelles is associated with Ago2/CAV1 interaction in the cancer cells." (PMID 38649663, 2024). "In this study, we showed that Cav-1 expression was increased in cancer cells that cultured on aligned fibers, suggesting that substrate topography might modulate cell behaviors and function in association with Cav-1." (PMID 39318372, 2024). "Additionally, CAV1-high tumors were associated with the dominance of carcinoma ecotype (CE) 6 followed by CE 1 (P<0.001), S6 Fig in S1 File." (PMID 38959243, 2024). "CD9, caveolin 1 (CAV1), tumor rejection antigen 1 (gp96), exosomal miRNAs (e.g., miR-486-5p, miR-486-3p, and miR-10b-5p are only secreted by cancer cells) have diagnostic value in HNSCC, and increased expression of HSP90, miR-31, miR-21, and MALAT1 are biomarkers for OSCC." (PMID 37046817, 2023). "Even with CAFs, we cannot neglect to mention paradoxical effects considering that CAFs can transfer high-energy metabolites (L-lactate, ketones, glutamine, and free fatty acids) to epithelial cancer cells via caveolin-1 (CAV-1) to promote cancer progression in a host–parasite association." (PMID 38006033, 2023). "CAV1 expression in tumors has been linked to radioresistance in several cancers." (PMID 37017811, 2023).
cancer (continued). "For example, fibroblast-derived caveolin-1, which promotes breast cancer cell elongation, directional migration and metastasis, is expressed by cancer associated fibroblasts (CAFs) and is an important consequence of cancer cell–CAF interaction." (PMID 37218922, 2023). "Moreover, compared to coculture with normal ESFs, coculture with CAV-1-deficient ESFs further promoted cancer cell EMT." (PMID 36604141, 2022). "Therefore, miR-1246 released into recipient cancer cells by extracellular vesicles reduces the expression of caveolin 1, which triggers the overexpression of P-gp1, causing resistance to paclitaxel." (PMID 35629286, 2022). "Indeed, the MAPK/ERK pathway increases caveolin-1 expression in cancer cells and, through the induction of RhoA/Rho-associated protein kinase 1 (ROCK1), promotes cell contraction and favors cancer cell migration along the pre-existing collagen matrix." (PMID 36497384, 2022). "The loss of stromal CAV1 upon PCa progression was further shown to be accompanied with a metabolic switch to aerobic glycolysis yielding lactate and pyruvate metabolites to fuel neighboring cancer cells and thus increasing their ATP production." (PMID 35155239, 2022). "Here, cancer cells induce Caveolin-1 deficient TAFs to conduct aerobic glycolysis and produce metabolites like lactate and pyruvate that cancer cells could then take up and process to derive energy for proliferation." (PMID 35814453, 2022). "According to the results from BioMuta-single-nucleotide variations in the cancer database, 45 modified residues and two modified functional residues of the CAV1 polymorphism have been recorded, and some of them have been reported to be correlated with digestive cancers." (PMID 34128850, 2021). "CAV-1 has also been implicated in navigating cell migration in stroma and cancer invasion." (PMID 34762666, 2021). "The high expression level of CAV1 in the cancer cells of CP compared to the other patterns, points also at a more aggressive behavior, as CAV1-expression has been associated with cancer cell proliferation and migration, chemoresistance and worse patient outcome." (PMID 33672734, 2021). "However, the association of caveolin-1 with protumoral or antitumoral mechanisms depends on the cancer subtype and organ of origin." (PMID 33037799, 2021). "Cav-1 is also closely implicated in the glycolytic metabolism of cancer cells." (PMID 34568078, 2021). "Taken together, our study not only highlights the novel function of CP formula in suppressing metastasis of HBV-associated HCC, but it also addresses the critical role of Cav-1 in mediating Akt/GSK3β/β-catenin axis to control the late-phase of cancer progression." (PMID 34168559, 2021). "Cav-1 overexpression in cancer has been linked with tumorigenesis and metastasis." (PMID 33920031, 2021). "In addition, CAV1 is a major structural protein in caveolae and reported as an integral membrane protein associated with the progression of carcinoma." (PMID 33712015, 2021). "Importantly, high epithelial Cav-1 expression was associated with a better overall survival (P < 0.001) and a delayed cancer onset time (P < 0.05)." (PMID 32528105, 2020). "Caveolin-1 is a protein that has been extensively characterized and has been shown to play an important role in the regulation/inhibition of various signaling pathways associated with cancer progression." (PMID 32321558, 2020). "Bearing this in mind, CAV1 presence or absence there may be associated with organelle dysregulation and the development of cancer." (PMID 32458269, 2020). "Cancer cell-derived ROS could down-regulate the expression of caveolin 1 (CAV1) in CAFs, and the loss of CAV1 also leads to increased ROS levels, thereby stabilizing HIF-1α." (PMID 32787888, 2020). "Meanwhile, Cav-1 has also been implicated in cancer metabolic modulation." (PMID 32528105, 2020). "Reversely, EMT is associated with Cav-1 expression in human cancer." (PMID 31297035, 2019).
cancer (continued). "In summary, CAV1 is implicated in cancer, both as a promoter and a suppressor of this disease." (PMID 31362353, 2019). "Thus, evidence available from several groups indicates that CAV1 is secreted by cancer cells and can promote the acquisition of traits associated with enhanced malignancy of such cells." (PMID 31362353, 2019). "CAV1 is positively associated with cancer stages, which may suggest that exosomal CAV1 transferred to recipient cells promotes cancer metastasis in vivo." (PMID 31355262, 2019). "Loss of CAV1 has been associated with a proinflammatory status in senescent endothelial cells and with premature senescence in fibroblasts and was protumorigenic for selected cancers, such as prostate and gastric cancer and glioblastoma." (PMID 30246033, 2018). "During cancer initiation, malignant transformation may be accelerated due to CAV1 loss, which would sensitize normal cells to oncogenic events." (PMID 30333750, 2018). "Given the strong association between inflammation and cancer, CAV1-KO mice may be useful for studies focusing on the intricate connections between inflammation and cancer." (PMID 30246033, 2018). "Loss of stromal Caveolin-1 (CAV1) expression is associated with poor prognosis in various cancers." (PMID 28515480, 2017). "It contributes to understanding the molecular impact of specific Cav-1 mutations in certain cancers where TrkA, p75NTR, and NGF are involved in the tumorigenic response, while raising the question of the potential impact on trafficking of other receptors and channels." (PMID 28338624, 2017). "Cav-1 signaling has also been implicated in cancer invasion and directional cell migration." (PMID 29221162, 2017). "In addition, loss of stromal Cav-1 expression in cancer-associated fibroblast (CAF) was reported at 35% in GC." (PMID 28828003, 2017). "Mutational alteration of the Cav-1 gene has been rarely found in human cancers." (PMID 29141593, 2017). "CAV1-deficient mice also displayed elevated eNOS expression and phosphorylation, and eNOS inhibitor could block Cav-1 loss-induced cancer growth, angiogenesis, and metastasis." (PMID 28546853, 2017). "Augmented CAV1 expression is frequently linked to enhanced metastatic potential of cancer cells." (PMID 29340103, 2017). "CAV1 expression is reduced in a variety of human tumors and CAV1 re-expression is often sufficient to attenuate functions associated with the transformed phenotype in cancer cells." (PMID 28099944, 2017). "Thus, the loss of stromal Cav-1 has been reported to be a poor prognostic factor in various human cancers." (PMID 28828003, 2017). "Notably, over-expression of ANXA1 and CAV1 has been associated with therapeutic resistance in different cancer settings." (PMID 27553366, 2016). "From a technical viewpoint, complementing CAV1 gain or loss of function studies with high throughput molecular biology methods, such as metabolomics, genomics and proteomics, will help to clarify its function in cancer cell metabolism." (PMID 27852311, 2016). "This proposition aligns with inverse association of CAV1 with autophagy induction as reported by some studies (discussed later), but does not establish a direct link between enhanced glutaminolysis and high CAV1 expression as also seen in cancer." (PMID 27852311, 2016). "Hence, cancer cells induce in CAFs oxidative stress and a glycolysis switch associated with Cav-1 downregulation." (PMID 27595103, 2016). "Besides earlier studies that implicated CAV1 in endocytosis, signaling and lipid disorders, research activities in the last two decades also focused on clarifying its relevance in cancer." (PMID 27852311, 2016). "Cav-1 has been well-reported to be associated with cancer and metabolism." (PMID 26627850, 2015). "Therefore, the value of Cav-1 as a diagnostic or therapeutic target to improve chemoresistance is still needed to be validated on independent cancer type." (PMID 26431273, 2015).
cancer (continued). "During cancer initiation, malignant transformation may be accelerated due to Cav-1 loss and this would sensitize normal cells to oncogenic events." (PMID 26431273, 2015). "First, studies show that Cav-1 is negatively associated with cancer cells’ transformation." (PMID 26431273, 2015). "Therefore, the underlying mechanisms between Cav-1 and cancer chemosensitivity modulation warrant study." (PMID 26431273, 2015). "Studies performed in different cancer models revealed that insulin treatment, c-Src kinase activation and integrin-mediated mechanotransduction cause tyrosine phosphorylation of CAV1 on tyrosine 14 (Y14), which appears to be essential for CAV1-driven cell migration." (PMID 25148256, 2014). "A rather speculative idea is that the dual role of CAV1 in cancer may be linked to its participation in the control of autophagy." (PMID 25328887, 2014). "Secondly, cancer associated fibroblasts (CAFs) may also express dysregulated Cav-1 and IGF system components." (PMID 25374561, 2014). "Considering the fact that Cav-1 was shown to reduce overtimes after cell detachment and this reduction was associated with the increase of cancer cell adhesion, at later time the metastatic cells may adhere and form secondary tumors." (PMID 23460862, 2013). "Caveolin-1 has also been widely associated as a prognostic marker in several cancers." (PMID 23894397, 2013). "Caveolin-1 (cav-1) has been implicated in the development of human cancers." (PMID 22200856, 2012). "Taken together, compelling experimental evidence has accumulated suggesting that endothelial Cav-1 may promote pathological angiogenesis associated with cancer and inflammation." (PMID 26605130, 2012). "On the other hand, CAV1 has also been implicated in the inhibition of cancer progression." (PMID 22152020, 2011). "The CAV1 gene is localised on chromosome 7, a highly conserved region that includes a known fragile site which is deleted or associated with loss of heterozygosity in a variety of human cancers." (PMID 22040717, 2011). "Research has shown that a genetic variant of Cav‐1, specifically the single‐nucleotide polymorphism rs4730751, is linked to elevated risks of all‐cause mortality, and higher risks of death from infections, cardiovascular disease, and accelerated cancer progression in AAV patients." (PMID 40778471, 2025). "Through Ago2/CAV1 interaction, Ago2 is recruited into a distinct region associated with plasma membranes or caveolae, which results in an increase in specific miRNAs and, in turn, increases miRNA-mediated translational suppression in distinct regions of cancer cells." (PMID 38649663, 2024). "In addition to CAV1, other metastasis‐promoting genes like Ras family proteins and tetraspanins also impact membrane composition, hence, membrane remodelling appears to be a common mechanism underlying release of pro‐metastatic EVs in cancers." (PMID 33931969, 2021). "Cav1 deficiency has also been reported to induce premature senescence via mitochondrial dysfunction, induce a switch from oxidative phosphorylation to glycolysis in response to oxidative stress and mediate stromal cell regulation of mitochondrial metabolism of cancer cells." (PMID 31803361, 2019). "Finally, the Cav-1-knockout fibroblasts metabolically cooperate with cancer cells by enhancing lactate production for mitochondrial respiration in anabolic cancer cells Taken as a whole, the loss of stromal Cav-1 is very important in the metabolic reprogramming of CAFs." (PMID 29967776, 2018). "Taken together, these results implicate acutely enhanced CAV1 expression following the treatment with anti-neoplastic drugs at sub-cytotoxic concentrations in promoting the acquisition of malignant traits associated with a more aggressive cancer cell phenotype." (PMID 29340103, 2017). "Thus both modes of regulation have been implicated in CAV1 silencing in cancer cells." (PMID 29340103, 2017).
cancer (continued). "We speculate that downregulation of caveolin-1 in cancer-associated fibroblasts may prevent the localization of m-AAA in mitochondria and m-AAA-dependent mitochondrial protein quality control with the consequent degradation of respiratory chain complexes and switch to aerobic glycolysis." (PMID 27705926, 2016). "Consistent with the hypothesis that loss of Cav-1 expression promotes more aggressive cancer phenotypes, rescue of Cav-1 expression in MCF7 cells led to a marked inhibition of anchorage-independent growth as determined by a reduction in colony formation in soft agar." (PMID 26543228, 2016). "Loss of stromal Cav-1 may be used as biomarker for cancer aggressiveness." (PMID 27595103, 2016). "Additionally, HDL may convey some protection from cancer severity by inhibiting the formation of lipid rafts which have been associated to procarcinogenic cell signaling through the activity of Caveolin-1(Cav-1)." (PMID 26377420, 2015). "As genome instability triggered by endogenous or exogenous DNA damaging agents is one of the main causes of cancer, loss or deficiency of Cav-1 at early stages of cancer development may cause a defect in DNA damage response leading to genomic alteration and oncogenic transformation." (PMID 20700465, 2010). "In this context, it is perhaps worth noting that phosphorylation at this same site appears important for regulation of caveolin-1 secretion and, hence, might provide a link to the secreted pool of caveolin-1 associated with metastatic potential of some cancer cells." (PMID 18400052, 2008). "Caveolin-1 (Cav-1) promotes anoikis resistance in cancer cells by stabilizing anti-apoptotic proteins like Mcl-1 and activating survival pathways such as Src/EGFR/ITGB1, PI3K/Akt, and MEK/ERK, facilitating anchorage-independent growth and metastasis." (PMID 41596231, 2026). "Proteins such as Mcl-1, Cav-1, Bcl-xL, and 14-3-3ζ are suppressors of anoikis, and their up-regulation induces anoikis resistance in cancer cells." (PMID 41596231, 2026). "In this study, cav-1 expression was decreased in both normal and cancer cells with the addition of OT." (PMID 39857963, 2025). "In metastatic breast cancer, Cav1-loaded EVs released by cancer cells, have been shown to confer pro-metastatic traits, such as enhanced invasion and migration to non-metastatic recipient cells." (PMID 40963741, 2025). "This suggests that during the development of TKI resistance, drug-tolerant CAV1+ cancer cells are selectively enriched." (PMID 40715090, 2025). "In contrast, upregulation of Cav-1 suppresses BKCa channel activity and reduces their surface localization, ultimately inhibiting cancer progression." (PMID 40358155, 2025). "Maintaining Cav-1 at a phosphorylated state by enhancing local kinase activity would be helpful to reduce mitophagy and metastasis, hence being applicable during cancer chemotherapy." (PMID 40148800, 2025). "Although fibroblasts exhibited higher CAV1 expression compared to epithelial cancer cells, the proportion of cancer cells substantially outweighed that of fibroblasts." (PMID 39482470, 2025). "It has been suggested that CAV1 is involved in the development and progression of many cancer types, including lung, cervical, and breast cancers, as well as in the invasion of cancer cells." (PMID 40419438, 2025). "Reducing Cav-1 expression diminishes this mitophagy, heightening the sensitivity of cancer cells to cisplatin." (PMID 39859167, 2025). "Collectively, these findings highlight Cav1’s multifaceted role in cancer drug resistance and EV dynamics." (PMID 40963741, 2025). "In contrast, our results revealed that CAV1 was expressed only in the clinical specimens from some of the patients, and it was expressed on the plasma membrane of cancer cells." (PMID 40419438, 2025). "For example, CAV1 has been indicated as both promoting and suppressing cancer progression in a variety of tissues." (PMID 39960760, 2025).